HOXA7 (homeobox A7)
Description:
Sequence-specific transcription factor which is part of a developmental regulatory system that provides cells with specific positional identities on the anterior-posterior axis.
Synonyms: HOX1A; ANTP; HOX1; HOX1.1
Tractability: PROTAC: ubiquitination databases record sites on it.
Gene: Protein-coding gene on chromosome 7 (27,153,716 to 27,157,936, reverse strand). Ensembl gene ENSG00000122592.
Subcellular location: Nucleus
Subcellular location (Human Protein Atlas): Nucleoplasm; Nuclear membrane
Gene Ontology:
Molecular function: DNA-binding transcription activator activity, RNA polymerase II-specific; DNA-binding transcription factor binding; protein binding; RNA polymerase II cis-regulatory region sequence-specific DNA binding; sequence-specific DNA binding; sequence-specific double-stranded DNA binding; DNA-binding transcription factor activity, RNA polymerase II-specific; DNA binding; DNA-binding transcription factor activity
Biological process: angiogenesis; negative regulation of cell-matrix adhesion; negative regulation of DNA-templated transcription; negative regulation of keratinocyte differentiation; negative regulation of leukocyte migration; negative regulation of monocyte differentiation; negative regulation of transcription by RNA polymerase II; positive regulation of transcription by RNA polymerase II; anterior/posterior pattern specification; regulation of transcription by RNA polymerase II; regulation of DNA-templated transcription
Cellular component: nucleoplasm; chromatin; nucleus
Genetic constraint (gnomAD): Loss-of-function variants: 16 observed, 15.38 expected, observed/expected ratio (o/e) 1.04, 90% interval 0.7 to 1.57. The upper end of that interval is the gene's LOEUF score, 1.57, which puts it in group 6 of 6, group 1 being the genes least tolerant of losing a copy. Missense variants: 338 observed, 316.24 expected, observed/expected ratio (o/e) 1.07, 90% interval 0.98 to 1.17. Synonymous variants: 154 observed, 141.86 expected, observed/expected ratio (o/e) 1.09, 90% interval 0.95 to 1.24.
Homologues: Orthologues: chimpanzee HOXA7 (99% identical), macaque HOXA7 (98% identical), dog HOXA7 (96% identical), pig HOXA7 (95% identical), rabbit HOXA7 (93% identical), mouse Hoxa7 (91% identical), rat Hoxa7 (90% identical), tropical clawed frog hoxa7 (66% identical). Paralogues in human: HOXB7 (56% identical), HOXB6 (41% identical), HOXA5 (40% identical), HOXB5 (39% identical), HOXA6 (38% identical), HOXC6 (38% identical), HOXC8 (36% identical), HOXD8 (36% identical), HOXA4 (34% identical), HOXB8 (34% identical), HOXC4 (34% identical), HOXD4 (34% identical), and 30 more.
Diseases named in the same sentence as HOXA7 in open-access papers:
HOXA7 is named in the same sentence as 68 diseases in open-access papers, as found by Europe PMC text mining. Sharing a sentence is not in itself a finding about the gene and the disease. The quoted sentences say what the papers report.
leukemia (24 papers, 2007 to 2025). A malignant (clonal) hematologic disorder, involving hematopoietic stem cells and characterized by the presence of primitive or atypical myeloid or lymphoid cells in the bone marrow and the blood. "This aberrant histone methylation at the MLL target gene loci causes overexpression of many Hox genes (e.g., HoxA7, HoxA9, and Meis1) that eventually cause leukemia initiation." (PMID 26970896, 2016). "This aberrant epigenetic event dysregulates the expression of many MLL target genes, such as HoxA9, HoxA7, and Meis1 whose overexpression can cause leukemia." (PMID 27316347, 2016). "Importantly, the NUP98 translocations that occur in AML all share the N-terminus of the protein and are thought to initially lead to epigenetic dysregulation of different leukemia-associated genes including HOXA7, HOXA9, and HOXA10 in myeloid precursor cells." (PMID 31467532, 2019). "The dysregulation of HOXA7 in ESCC is associated with a poorer prognosis, echoing findings from mixed-lineage leukemia, where HOXA7 overexpression correlates with lower survival rates." (PMID 39596630, 2024). "ChIP–seq profiling of Stat5a, Runx1 and Runx2 confirmed the motif analysis, demonstrating cobinding of these transcription factors and BAF or MLL1 and MLL4 complexes at key pro-leukemia genes including Hoxa7 and Hoxa9." (PMID 37580596, 2023). "In MLL-AF9-related leukemia, HOXA7 gene expression was potentially involved in the differentiation blockage." (PMID 33299888, 2020). "We also observed a moderate correlation of WBP5 expression with the levels of HOXA7, another gene that was reported to influence leukaemia latency and phenotype and is required for efficient immortalization of myeloid cells by MLL-ENL fusions." (PMID 32103106, 2020). "Previous research has shown that the gene HOXA7 is overexpressed in MLL-fusion leukemias, which commonly have very poor outcomes." (PMID 33134167, 2020). "HOXA7 and HOXA9 appear to be required for efficient in vitro myeloid immortalization via the replacement of leukemia-associated fusion proteins with MLL fusion proteins." (PMID 31426381, 2019). "Changes in gene expression following Bcor mutation in the non-transformed and malignant settings were significantly correlated, with key TFs Hoxa7, Hoxa9 and Tal1 also upregulated in the context of leukaemia." (PMID 30902969, 2019). "Thus, FLT3 expression was associated with HOXA5, HOXA7, HOXA9 and MEIS1 in human leukemia and this gene expression profile was confined to leukemia with either intermediate or unfavorable cytogenetics." (PMID 17712416, 2007). "HOXA9, HOXA10, and HOXA7 are induced by MLL-AF4 and HOXA9 is required for MLL-rearranged leukemia survival." (PMID 34321607, 2022). "Mechanistically, these anti-leukemia effects of I-BET151 are likely due to its suppression of ZM-activated pro-leukemic genes, including Hoxa7, Hoxa9, Meis1, Myc and Myb." (PMID 33594072, 2021). "Compared to levels in Hoxa9/Meis1 leukemias, endogenous Hoxa9 and Hoxa10 were considerably elevated in SQSTM1-NUP214 leukemias, whereas the levels of Hoxa3, Hoxa5, Hoxa7, Hoxa11 and Meis1 were comparable in Hoxa9/Meis1 and SQSTM1-NUP214 leukemias." (PMID 32343715, 2020). "Together, this demonstrates unique dependency on a subset of the Hoxa cluster (Hoxa7, Hoxa9, Hoxa10, and Hoxa11) genes for maintenance of MA9 leukemia." (PMID 31861091, 2019). "Even so, it is known that the HOXA10 gene has oncogenic potential in developing leukemia; specific roles of HOXA5, HOXA7, and HOXA10 in myeloid leukemias are poorly described." (PMID 31681584, 2019). "Recent genome-wide ChIP-seq analyses identified various sets of direct target genes of MLL-FP, which consistently included the master regulatory factors (HOXA7, HOXA9, HOXA10, and MEIS1) required for the development of MLLr-leukemias." (PMID 29692408, 2018).
leukemia (continued). "The finding that HLF also correlated with HOXA7 and HOXA9 in human leukemia suggests that this gene also might be important for Hox induced cell transformation and development of leukemia." (PMID 17712416, 2007). "Analysis of the selected Hox A cluster and Hox cofactor genes revealed a high degree of co-expression between these in leukemia samples, where correlation coefficient between HOXA5, HOXA7, HOXA9 and MEIS1 ranged between 0.83 and 0.92 (Spearman rank correlation, p<0.0001 in all cases)." (PMID 17712416, 2007). "Ash1l, Ctnnb1, Hoxa7, and Hoxa9 were also upregulated in the single mutant Mir-142−/− GMPs compared to WT, but the key co-factors Meis1 and Pbx3 were not, potentially explaining why these mice failed to develop leukemia." (PMID 33173219, 2020). "The MLL-AF9 fusion protein, which interacts with p-TEFb/DOT1l, is not capable of inducing leukemia in recipient mice when introduced into Hoxa9 deficient cells, while the cytoplasmic fusion MLL-GAS7 is capable of driving leukemia in cells deficient for either Hoxa9 or Hoxa7." (PMID 27007052, 2016). "However, their expression did not correlate with HOXA5, HOXA7, HOXA9 or MEIS1 and only weakly with PBX3 expression in human leukemia (Spearman, r = 0.37, p = 0.033 and r = 0.44, p = 0.078 respectively)." (PMID 17712416, 2007).
breast carcinoma (12 papers, 2014 to 2024). "Overexpression of the HOXA7 gene can increase the proliferation of liver cancer, breast cancer, and granulosa cells, which was expected to become an important molecular target for the diagnosis and treatment of liver cancer." (PMID 34169093, 2021). "MTERFD1 is closely related to breast cancer recurrence and HOXA7 plays a critical role in regulating the proliferation of ER-positive cancer cells." (PMID 32854705, 2020). "In early-stage breast cancer patients, low levels of TET1 mRNA were associated with poor survival rates, and in breast cancer cell line and mouse xenograft models, TET1 was reported to regulate tumor growth and metastasis by demethylating HOXA7 and HOXA9 promoter regions." (PMID 36979633, 2023). "However, HOXA7 was recently more reported to be oncogene and promoted oncogenic characteristics in many kinds of tumors such as liver cancer, cervical cancer, ovarian cancer, colorectal cancer and breast cancer." (PMID 36387262, 2022). "In breast cancer, TET1 has been shown to impair HOXA7 function by modulating HOXA promoters, thereby promoting breast tumor growth and metastasis." (PMID 39596630, 2024). "Among the genes amplified in the focal regions were a cluster of HOX genes (HOXA7, HOXA9, HOXA10, HOXA11) on 7p15, AKT1 (14q32.33), IGF1R (15q26.3), ERBB2 and NEUROD2 (17q12), all of which have been reported in primary breast cancers." (PMID 24489661, 2014). "Subsequent to TET1 gene expression, TET1 auto-demethylates its promoter and, subsequently, the demethylation of the promoter of homeobox A (HOXA) genes, HOXA7 and HOXA9, culminating in the effect from the TET1, HOXA7, and HOXA9 genes suppressing breast cancer invasion and metastasis." (PMID 38994941, 2024). "We predicted that 6 genes including ANXA1 would be regulated by miR196a using 4 prediction softwares (TargetScan, MiRanda, Diana MicroT and PicTar), and confirmed the reduction of these genes (ANXA1, HOXA7, HOXB7, ING5, CDC73 and SMURF1) by miR-196a in breast cancer cells using qPCR analysis." (PMID 27105503, 2016). "For example, miR-196a has been studied for its oncogenic roles in glioblastoma, pancreatic adenocarcinoma, breast cancer, oesophageal adenocarcinoma, and colorectal cancer, and shown to target HOX family genes (HOXA7, HoxB7, HOXC8, HOXB8, HOXD8), ERG, HMGA2, ANXA1, S100A9, SPRR2C, KRTS." (PMID 24621885, 2014). "The low expression of HOXA7 methylation also exists in breast cancer cells, while the normal expression of HOXA7 methylation in normal tissues adjacent to breast cancer, ndicating that HOXA methylation expression plays an important role in the occurrence and development of breast cancer." (PMID 33363022, 2020).
lung carcinoma (11 papers, 2014 to 2025). "As elevated odds ratios ranged from 2.81 to 7.19, logistic regressions analyses also indicated that the methylation of CDO1, TAC1, SOX17, and HOXA7 were closely related to increasing lung cancer risk." (PMID 32138766, 2020). "It turned out that the expressions of B3GNTL1 and HOXD8 were significantly upregulated, while the expression of remaining five genes (HOXB4, ZNF808, ITGA4, PTGER4, and HOXA7) were significantly downregulated in lung cancer tissues (p < 0.01)." (PMID 37101220, 2023). "In this current study, we found that HOXA7 DNA methylation was correlated with higher NDI, and methylation of HOXA7, SOX17, ZFP42, HOXA9, CDO1 and TAC1was associated with advanced stage disease in lung cancer." (PMID 39107707, 2024). "We identified 7 DMRs corresponding to 7 differentially methylated genes (DMGs) including HOXB4, HOXA7, HOXD8, ITGA4, ZNF808, PTGER4, and B3GNTL1 that were highly associated with lung cancer by comparing the methylation profiles of lung cancer and benign nodule tissue." (PMID 37101220, 2023). "Promoter methylation of eight lung cancer-specific genes (CDO1, TAC1, SOX17, HOXA7, HOXA9, GATA4, GATA5, and PAX5) was detected using nanoparticle-based DNA extraction (MOB) followed by qMSP." (PMID 32138766, 2020). "While many biomarkers have been shown to be viable for gastric and urinary cancers such as bladder and CRC, one study also reported a successful DNA methylation analysis (1.7) of a panel (CDO1, TAC1, HOXA7, HOXA9, SOX17, and ZFP42 promoters) to diagnose lung cancer." (PMID 40141826, 2025). "In lung cancer, two HOX genes, HOXA7 and HOXB4, were highly methylated." (PMID 24842468, 2014). "Reverse transcriptase-polymerase chain reaction (RT-PCR) showed that HOXA7 and HOXA9 mRNAs were significantly overexpressed in esophageal squamous cell carcinoma tissues compared to non-cancerous surrounding tissues, while HOXA9 was epigenetically downregulated in lung cancer." (PMID 32296636, 2020). "However, there is a lack of research on the role of HOXA7 in the brain metastasis of lung cancer." (PMID 35693013, 2022). "This confirmed the utility of CDO1, TAC1, HOXA7, and SOX17, while newly tested genes were not as effective for lung cancer detection." (PMID 32138766, 2020).
cervical cancer (7 papers, 2014 to 2023). A primary or metastatic malignant neoplasm involving the cervix. "HOXA7 has been found to be associated with the development and progression of cervical cancer and hepatocellular carcinoma." (PMID 37834206, 2023). "For instance, circSLC26A4 promotes cervical cancer progression through regulating miR-1287-5p/HOXA7." (PMID 34224315, 2021). "For example, circSLC26A4 could accelerate cell proliferation and invasion via absorbing miR‐1287‐5p/HOXA7 in cervical cancer." (PMID 33184989, 2020). "Moreover, circSLC26A4 promoted the progression of cervical cancer via the miR-1287-5p/HOXA7 axis." (PMID 33413360, 2021).
colorectal cancer (7 papers, 2014 to 2024). A primary or metastatic malignant neoplasm that affects the colon or rectum. "Additionally, HOXA7 has been reported to be overexpressed in colorectal cancer, which is also linked to poor prognoses." (PMID 39596630, 2024). "By downregulating HOXA7 and promoting cell migration and invasion, miR-196a plays a pro-cancer role in colorectal cancer." (PMID 35693013, 2022). "In colorectal cancer, miR-196a inhibited the expression of HOXA7, HOXB8, HOXC8 and HOXD8 genes, leading to AKT pathway activation and increased cell motility." (PMID 29259267, 2017). "However, suppressing CTCF in human colorectal cancer cell line HCT116 notably reduced HOXA7 and HOXA9 expression, consistent with the finding in MLLr AML cell line MOLM13." (PMID 33001025, 2020).
ovarian carcinoma (7 papers, 2009 to 2022). A malignant neoplasm originating from the surface ovarian epithelium. "Among these genes, HOXA7 was one of the HOX genes most consistently overexpressed in ovarian cancers." (PMID 20540809, 2010). "HOXA7 was also non-specifically expressed in all sub-types of high grade ovarian carcinoma and the presence of HOXA7 was associated with a lower grade phenotype." (PMID 31382546, 2019). "Overexpression of HOXA7 was also detected in ovarian carcinomas." (PMID 20540809, 2010). "Thus, anti-HOXA7 AAbs represent potential serum biomarkers, particularly for detecting small, early-stage ovarian carcinomas." (PMID 20145720, 2009). "LncRNA HOTAIR can facilitate the expression of Homeobox A7 (HOXA7) and sponge miR-138-5p to rescue EZH2 and sirtuin 1 (SIRT1) expression in ovarian cancer, both of which contribute to cisplatin resistance." (PMID 34660304, 2021). "The homeobox transcription factor genes HOXA7, HOXA9, HOXA10, and HOXA11 have an important role in the morphologic heterogeneity of epithelial ovarian cancers and their assumption of mullerian-like features." (PMID 20145720, 2009). "Nevertheless, although the anti-HOXA7 AAb assay alone allows no distinction between benign and malignant ovarian tumors, it is able to discriminate patients with well-to moderately differentiated ovarian carcinomas from healthy women." (PMID 20145720, 2009).
glioma (6 papers, 2016 to 2025). A benign or malignant brain and spinal cord tumor that arises from glial cells (astrocytes, oligodendrocytes, ependymal cells). "In gliomas, a type of brain tumour, the telomere-related gene HOXA7 exhibits significant roles in tumour development." (PMID 41327336, 2025). "Hox genes (HOXA2, HOXA5, and HOXA7) can regulate several hallmarks of cancer in malignant glial tumors." (PMID 37397378, 2023). "CD133 (p = 0.021) and HOXA7 (p = 0.001) were independent prognostic markers when the three glioma patient cohorts were combined (n = 231)." (PMID 28055976, 2017). "In brain tumors, HOXA7 is involved in glioma progression and affects patient prognosis." (PMID 35693013, 2022). "In this study, a three-gene signature (MN1, HOXA7, and SLC2A4RG) could divide lower grade glioma patients into low-and high-risk groups, with longer OS obtained in the former group." (PMID 27677590, 2016). "HOXA7 knockdown via HOXA7-siRNAclearly inhibited glioma cell migration and invasion." (PMID 27677590, 2016). "In the present study, we found that HOXA5, HOXA7, HOXA10, HOXC4 and HOXC6 are prognostic markers in glioma patients." (PMID 28055976, 2017). "These HOX genes are themselves prognostic markers in glioma, while the prognostic value for CD133 and HOX genes are mostly interdependent, with the exception of HOXA7." (PMID 28055976, 2017). "Three genes (HOXA7, SLC2A4RG and MN1) were selected to establish a three-gene signature in lower grade gliomas." (PMID 27677590, 2016). "HOXA7 (homeobox A7) was also selected by sCCA and HOXA7 knockdown inhibits glioma cell migration." (PMID 38790260, 2024). "Importantly, we found that CD133 expression in glioma was highly correlated with the expression of HOX gene stem cell factors (HOXA5, HOXA7, HOXA10, HOXC4 and HOXC6)." (PMID 28055976, 2017). "Moreover, HOXA7-siRNA inhibited migration and invasion in vitro, and downregulated MMP9 at the protein level in U251 glioma cells." (PMID 27677590, 2016).
liver cancer (6 papers, 2017 to 2022). An epithelial or non-epithelial malignant neoplasm that arises from the liver. "HOXA7 significantly enhanced proliferation, migration, invasion in vitro, and tumor growth and metastasis in vivo in liver cancer." (PMID 35342423, 2022). "The activation of Snail molecules was an important mechanism for HOXA7 to perform its oncogenic characteristics for liver cancer cells." (PMID 35342423, 2022). "Tang found that differential expression levels of HOXA7 were correlated with metastasis and prognosis of liver cancer and those levels indicated an acceleration of liver cancer cells migration and invasion." (PMID 29285211, 2017). "HOXA7 overexpression enhanced proliferation, migration, invasion and metastasis of liver cancer." (PMID 29631562, 2018).
esophageal squamous cell carcinoma (4 papers, 2013 to 2024). Esophageal squamous cell carcinoma (ESCC) is a type of esophageal carcinoma (EC) that can affect any part of the esophagus, but is usually located in the upper or middle third. "Deregulated expression of HOX genes including HOXB8, HOXC8, HOXD8 and HOXA7 in esophageal squamous cell carcinoma have been reported, and miR-196a is significantly up-regulated in pancreatic, breast, and esophageal cancer." (PMID 23967217, 2013). "For instance, it was found that HOXA7 and HOXA9 mRNAs were elevated in esophageal squamous cell carcinoma tissues." (PMID 35349479, 2022).
oral cancer (4 papers, 2022 to 2025). "Also, HOXA7 is upregulated in the ceRNA network in oral squamous cell carcinoma, increasing the invasion and migration of oral cancer cells." (PMID 35693013, 2022). "In contrast, HOXA7, HOXA10, HOXB7, HOXC6, HOXC10, HOXD10, and HOXD11 were consistently upregulated in potentially malignant oral lesions as they advanced to oral cancer." (PMID 41477365, 2025). "HOXA7, HOXA10, HOXB7, HOXC6, HOXC10, HOXD10, HOXD11 showed consistent upregulation in the potentially malignant oral lesions through their progression to oral cancer, which indicated the posterior prevalence of the HOX genes during cancer progression." (PMID 35710803, 2022).